PIK3CA (phosphatidylinositol-4,5-bisphosphate 3-kinase catalytic subunit alpha)
Diseases named in the same sentence as PIK3CA in open-access papers (continued):
Sharing a sentence is not in itself a finding about the gene and the disease.
skull base meningioma (3 papers, 2020 to 2025). A meningioma that arises from the skull base. "In cases of NF2-mutant skull base meningiomas refractory to surgery and radiation, currently, there is no effective chemotherapy; however, PIK3CA, SMO and AKT1 represent promising future therapeutic targets." (PMID 40075786, 2025). "Concerning the three NF2-wild type IVMs, none had mutations in AKT1, PIK3CA or SMO genes, which are typically altered in skull base meningiomas." (PMID 35049691, 2022).
Stroke (3 papers, 2021 to 2025). Sudden impairment of blood flow to a part of the brain due to occlusion or rupture of an artery to the brain. "In the process of stroke, PIK3CA and PIK3R1 are the main genes that promote cell survival and reduce cell apoptosis." (PMID 38013375, 2023). "PIK3CA was the only common target of key constituents and candidate stroke/TRFS targets, which may play an extremely important role in the treatment of XLCQ acting on stroke complicated with TRFS and needed to be focused on in the further experiment." (PMID 34335236, 2021).
thyroid nodule (3 papers, 2020 to 2025). A small circumscribed mass in the THYROID GLAND that can be of neoplastic growth or non-neoplastic abnormality. "In addition, TSHR, TTN, PIK3CA, and EIF1AX mutations in thyroid nodules categorized as indeterminate are uncommon and are typically verified as benign." (PMID 40586006, 2025).
tongue cancer (3 papers, 2019 to 2021). A malignant neoplasm affecting the tongue. "In the HPV positive group there was one patient with PIK3CA mutations (1/26, 3.85%), diagnosed with tongue cancer and abnormal expression of p16 protein." (PMID 34072735, 2021). "Alterations in ANO1, NUDCD1, PIK3CA defined survival in tongue cancer patients with nodal metastasis (node+ECS-), while EPS8 is a significant differential in node+ECS- laryngopharyngeal cancers." (PMID 31310629, 2019).
tongue tumors (3 papers, 2017 to 2024). "Orthotopic tongue tumor xenografts were established from CAL27 wild-type (WT) or PIK3CA H1047R-expressing cells." (PMID 35790753, 2022).
vascular tumor (3 papers, 2021 to 2025). "PIK3CA mutations are seen not only in LMs but other vascular anomalies, highlighting the role of PIK3CA activation in angiogenesis, lymphangiogenesis, and vascular neoplasms." (PMID 35787784, 2022).
vulvar squamous cell carcinoma (3 papers, 2020 to 2024). An invasive squamous cell carcinoma arising from the vulva. "PIK3CA mutations are most frequently (25.6%) found in HPV-related cancers, such as oropharyngeal, cervical, anal and vulvar squamous cell carcinomas." (PMID 32664330, 2020).
adenosarcoma (2 papers, 2017 to 2019). A low grade malignant neoplasm characterized by the presence of a benign epithelial component (tubular and cleft-like glands) and a low grade sarcomatous component that contains varying amounts of fibrous and smooth muscle tissues. "In our cohort of adenosarcomas, we detected alterations in PI3K pathway in 26% (5/19) of cases (PIK3CA, PIK3CG, PIK3R1, PTEN mutations and/or amplification of AKT2 or ERBB3)." (PMID 28267263, 2017).
asthma (2 papers, 2019 to 2022). "Among these components, caffeic acid might be recognized as an essential active compound in H. cuspidatus containing multiple targets, including STAT3, EGFR, and PIK3CA, that contributed to treating asthma." (PMID 35572723, 2022).
cardiac tumor (2 papers, 2018 to 2024). "To investigate the effect of PIK3CA (H1047R) on activation of protein kinase B/Akt signaling pathway, we tested the phosphorylation of pathway members by western blotting in cardiac tumor tissues." (PMID 30062063, 2018).
cavernoma (2 papers, 2022 to 2023). "Moreover, in other pathologies such as familial cavernomatosis, it has recently been described that somatic mutations in PIK3CA trigger the growth and bleeding of cavernomas that lead to surgeries." (PMID 37843608, 2023). "Recently, gain-of-function Pik3ca mutations have been shown to be sufficient to drive small, postnatal capillary hemangiomas in brain endothelial cells and are necessary, in combination with mutations of known CCM genes in mice or in humans, for the development of large postnatal cavernomas." (PMID 36353506, 2022). "P-S6, a downstream effector of AKT/mTOR, was no longer active in most of the adult cavernoma-like vascular lesions we observed in mice with mutant Pik3ca in cells having once expressed Egr2/Krox20." (PMID 36353506, 2022).
chronic myelogenous leukemia (2 papers, 2010 to 2019). "The best examples of the success of this screening method include the identification of the role of BCR and ABL as lethal hits in chronic myelogenous leukemia (CML) cell line KBM7, KRAS and PIK3CA and as lethal hits in colorectal cancer cell lines DLD-1 and HCT116." (PMID 30636933, 2019).
Crohn disease (2 papers, 2023). A gastrointestinal disorder characterized by chronic inflammation involving all layers of the intestinal wall, noncaseating granulomas affecting the intestinal wall and regional lymph nodes, and transmural fibrosis. "We compared the frequency of alterations in all recurrent genes in CAC by IBD subtype, and PIK3CA and IDH1 alterations were significantly enriched in patients with a history of Crohn’s disease versus ulcerative colitis." (PMID 36611031, 2023). "However, at least some molecular findings found in our SB-PCC cases, such as the lack of KRAS and PIK3CA point mutations, are likely histotype dependent, as they are observed in SB-PCCs with or without Crohn disease and are not a feature of Crohn disease–associated SBAs in general." (PMID 36812376, 2023).
cylindroma (2 papers, 2020 to 2021). "Comparison of CYLD-wildtype AC with vs. without cylindroma-like histology revealed that cylindroma-like cases showed significantly lower frequency of PIK3CA (9% [3/34] v." (PMID 32461623, 2020).
diffuse intrinsic pontine glioma (2 papers, 2021 to 2024). A neuroglial tumor that arises from the middle portion of the brain stem. "The brain penetrant pan-PI3K inhibitor paxalisib targets PIK3CA and shows enhanced efficacy with radiotherapy, enzastaurin, and metformin in diffuse intrinsic pontine glioma." (PMID 38319732, 2024). "In diffuse intrinsic pontine glioma (DIPG—also called diffuse midline gliomas), H3K27M mutations, as well as ACVR1, FGFR1, MET, and PIK3CA mutations, were clonal." (PMID 33673104, 2021).
diffuse midline glioma (2 papers, 2021 to 2022). A diffuse glioma that arises from the midline structures of the central nervous system. "The third patient with diffuse midline glioma, H3 K27M-mutant, was also found to have PIK3CA mutation within a highly conserved helical domain, and an ACVR1 mutation within the kinase domain." (PMID 34257334, 2021).
emphysema (2 papers, 2019 to 2021). "The cytosolic transport (RNF126, PLEKHJ1, VPS51, and AP1G1), target of rapamycin (mTOR) signaling (PIK3CA, STK11, RPS6KB2, and PRR5), regulation of translation, metabolic regulation, and apoptosis are involved in the percent emphysema-associated network." (PMID 34777474, 2021). "The purpose of this study was to evaluate PD-L1, FGFR1, PIK3CA, PTEN, and p16 expression in SCC associated with emphysema and COPD." (PMID 31481045, 2019). "There were no other significant associations between PD-L1, FGFR1, PIK3CA, PTEN, and p16 expression and total/local severity of emphysema or presence of COPD/GOLD stage." (PMID 31481045, 2019).
ependymoma (2 papers, 2019 to 2023). A WHO grade II, slow growing tumor of children and young adults, usually located intraventricularly. "The specific variants we found in the present ependymoma case such as inTP53, HRAS, SMAD4, PIK3CA are not in TCGA projects." (PMID 32612806, 2019).
epidermal nevus (2 papers, 2022). "In addition, isolated epidermal nevus can carry PIK3CA mutations." (PMID 35740480, 2022). "Other vascular diseases associated with PIK3CA mutation such as KTS and CLOVES were excluded due to lack of clinical phenotypes including low-low vascular lesions, congenital lipomatous overgrowth, and epidermal nevus." (PMID 34980271, 2022).
fallopian tube cancer (2 papers, 2018 to 2020). A primary or metastatic malignant neoplasm that affects the fallopian tube.
ganglioglioma (2 papers, 2022 to 2025). A well differentiated, slow growing neuroepithelial neoplasm composed of neoplastic, mature ganglion cells and neoplastic glial cells. "This tumour harbours a PIK3CA mutation, consistent with the molecular genetic profile frequently associated with gangliogliomas." (PMID 41033792, 2025).
hamartoma (2 papers, 2018 to 2022). A benign and excessive tumor-like growth of mature cells and normal tissues which grow in a disorganized pattern. "We have observed that benign vascular and/or hamartoma-like tumors arise postnatally in mice expressing constitutively active Pik3ca in a mosaic fashion, in cells having expressed the Krox20/Egr2 or Sox10 transcription factors." (PMID 36353506, 2022).
Hemihypertrophy (2 papers, 2022 to 2024). Isolated hemihyperplasia is a rare overgrowth syndrome characterized by an asymmetric regional body overgrowth, involving at least one limb, and associated with an increased risk of developing embryonal tumors principally nephroblastoma (see this term) and hepoblastoma. "LN commonly affects the median nerve in the wrist and palm, resulting in excessive growth within the nerve territory, such as macrodactyly and hemihypertrophy, and is also associated with PIK3CA mutations." (PMID 38378686, 2024).
Histiocytosis (2 papers, 2021 to 2023). An excessive number of histiocytes (tissue macrophages). "The discovery of additional mutations in LCH including A-RAF, N/KRAS, PIK3CA, and gene fusions involving B-RAF, ALK, and NTRK enrich the variegate landscape of the histiocytosis and further complicate the therapeutic choice." (PMID 34944576, 2021).
hypopharyngeal carcinoma (2 papers, 2016 to 2017). Carcinoma, predominantly squamous cell, arising from the epithelial cells of the hypopharynx. "Mutations of PIK3CA were found in 13.6% of hypopharyngeal carcinoma, and the E545K and H1047R mutant sites, two of hotspots mutations of PIK3CA, have been demonstrated that they can increase PIK3CA kinase activity and promote cellular transformation." (PMID 29156722, 2017). "Moreover, PIK3CA (H1047R) mutation was associated with a better clinical outcome in laryngeal and hypopharyngeal carcinoma patients." (PMID 27119232, 2016).
immunodeficiencies (2 papers, 2018 to 2021). "It is likely that additional mutations in PIK3CD will be discovered that mimic previously discovered oncogenic mutations in PIK3CA, highlighting the need to sequence the entire PIK3CD gene in patients presenting with complex immunodeficiencies." (PMID 29616047, 2018).
inflammatory bowel disease (2 papers, 2015 to 2025). A spectrum of small and large bowel inflammatory diseases of unknown etiology. "Our patient’s case illustrates this sporadic pattern well, as he had no family history of cancer, he tested negative for KRAS, NRAS, BRAF, and PIK3CA mutations, and he showed no signs of inflammatory bowel disease." (PMID 41487588, 2025).
intraductal papilloma (2 papers, 2023 to 2025). An intraluminal papillary epithelial neoplasm arising within the ducts. "Although PIK3CA or AKT mutations are more common in breast intraductal papilloma, AKT1 E17 K mutation was detected in intraductal papilloma of minor salivary glands, and no genetic alterations (BRAF, PI3KCA etc.)were detected in salivary glands intraductal papilloma with previous reports." (PMID 40013097, 2025).
ischemic stroke (2 papers, 2022). A stroke disorder caused by obstruction of blood flow to the brain, due to thrombotic (local blood clot formation) or embolic (due to a blood clot or other material traveling from another site) event. "Notably, MAPK3, MAPK1, HSP90AA1, STAT3, PIK3R1, PIK3CA, and AKT1 were the main target proteins involved in the pathogenesis of ischemic stroke with Qi deficiency and blood stasis syndrome." (PMID 35401166, 2022). "Therefore, the most significant 4 genes were PIK3CA, IL6, TNF, and KNG1, which means these molecules may function as important immune regulators in the inflammatory response following ischemic stroke." (PMID 35419038, 2022).
kaposiform hemangioendothelioma (2 papers, 2023). Kaposiform hemangioendothelioma is a very rare, aggressive, vascular tumor manifesting in the neonatal period or in infancy as cutaneous vascular tumors to large infiltrative lesions. "Lymphatic malformations (LMs) are associated with mutations of the PIK3CA (phosphatidylinositol-4,5-bisphosphate 3-kinase catalytic alpha subunit) gene, while Kaposiform Hemangioendothelioma (KHE) is associated with the GNA14 (G protein alpha subunit 14) mutation." (PMID 38201347, 2023).
large cell carcinoma (2 papers, 2009 to 2026). A malignant epithelial neoplasm composed of large, atypical cells. "Large cell carcinoma line NCI-H460 had both KRAS and PIK3CA mutations." (PMID 19238210, 2009).
leiomyosarcoma (2 papers, 2023 to 2025). An uncommon, aggressive malignant smooth muscle neoplasm, usually occurring in post-menopausal women. "In addition, the model demonstrated plasticity by generating leiomyosarcoma and osteosarcoma subtypes when driven by other genes such as CDK4 and PIK3CA." (PMID 41123840, 2025).
mesonephric adenocarcinoma (2 papers, 2019 to 2020). An adenocarcinoma of the cervix or the vagina arising from mesonephric remnants. "PIK3CA mutations, which have never been found in mesonephric adenocarcinoma, were identified in nearly half of MLAs." (PMID 33235131, 2020).
mesothelioma (2 papers, 2015 to 2020). A usually malignant and aggressive neoplasm of the mesothelium which is often associated with exposure to asbestos. "However, mutations in MAP kinase pathway genes, including RAS and PIK3CA are very rare in human mesothelioma." (PMID 26680231, 2015). "Both PI3K genes, PIK3CA and PIK3CD, all 3 AKT genes, AKT1, AKT2 and AKT3, as well as BCL2 gene were detected in mesothelium and mesothelioma samples." (PMID 32664372, 2020).
metabolic dysfunction-associated steatotic liver disease (2 papers, 2022 to 2024). Metabolic dysfunction-associated steatotic liver disease (MASLD, formerly known as nonalcoholic fatty liver disease or NAFLD) is a type of liver disease that is not caused by alcohol. "Of note, we observed that non-alcoholic fatty liver disease was involved in PIK3CA mutant CRC disease." (PMID 38848145, 2024).
migraine (2 papers, 2022). "PIK3CA, PIK3CB, and PIK3CD are important genes involved in cell proliferation, G protein-coupled receptor signal transduction, and cancer gene expression, and they may be related to migraine caused by glial neuron tumors." (PMID 36479181, 2022). "Such active ingredients may influence neuroactive ligand-receptor interaction, calcium signaling pathways, signaling pathways in cancer, cAMP signaling pathways, and PI3K pathways by acting on multiple targets such as PTGS2, PIK3CA, PIK3CB, PIK3CD, F2, and AR to treat migraine." (PMID 36479181, 2022).
myopia (2 papers, 2023 to 2025). "Research indicates that this pathway’s activation in experimental myopia models leads to increased expression of PIK3CA, AKT, and ERK1/2, resulting in retinal fibrosis and reduced thickness, highlighting its role in the fibrotic changes and functional impairments associated with myopia." (PMID 40933557, 2025). "The 6 important intersectional targets of DZP for myopia treatment were STAT3, PIK3CA, PIK3R1, MAPK1, MAPK3, and HSP90AA1." (PMID 37747014, 2023).
neuroendocrine neoplasm (2 papers, 2018 to 2020). Endocrine tumors, also referred to as neuroendocrine tumors (NETs), are defined by a common phenotype which is characterized by the expression of general markers (neuron specific enolase, chromogranin, synaptophysin) and hormone secretion products. "In addition, we identify amplified PIK3CA and RICTOR as potential biomarkers for patients with neuroendocrine tumors with increased propensity to respond to treatment with AKT inhibitors." (PMID 29951225, 2018). "In addition, our data suggest that PIK3CA and RICTOR gene co-amplification may define a unique subset of patients with neuroendocrine tumors that will respond to AKT inhibitors, and could thus be used as an additional biomarker for treatment stratification." (PMID 29951225, 2018).